ESRP1 (epithelial splicing regulatory protein 1)
Diseases named in the same sentence as ESRP1 in open-access papers (continued):
Sharing a sentence is not in itself a finding about the gene and the disease.
melanoma (19 papers, 2016 to 2025). A malignant, usually aggressive tumor composed of atypical, neoplastic melanocytes. "Their research demonstrated that melanoma with lower ESRP1 expression, which is associated with higher immune cell cytotoxicity, is more likely to respond to immune checkpoint blockade therapy." (PMID 40046628, 2025). "AS of epithelial splicing regulatory protein 1 (ESRP1) was correlated with tumor-associated immune cytolytic activity in malignant melanoma." (PMID 33996533, 2021). "Recent findings in melanoma patients identified a link between low ESRP1 expression in tumor tissue and tumor-associated immune cytolytic activity with better patient survival." (PMID 27650542, 2016). "Understanding the specific role of ESRP1 in melanoma may help reveal the molecular mechanisms underlying melanoma occurrence and development, providing new insights for future treatment strategies." (PMID 40046628, 2025). "In melanoma, low ESRP1 expression was correlated with greater tumor-associated immune cytolytic activity and patients with low ESRP1 expression showed a favorable survival, suggesting the potential utility of ESRP1 as a biomarker in predicting response to immunotherapy." (PMID 38110955, 2023). "Public database analyses revealed the association between high ESRP1 expression and poor prognosis of melanoma; however, the role of ESRP1 in melanoma remains unknown." (PMID 38110955, 2023). "In addition, in TCGA patients with melanoma, reduced levels of ESRP1 (which encodes a master splicing regulator involved in EMT) were correlated with increased immune checkpoint expression (PD-L1 and CTLA4) and elevated tumor-associated immune cytolytic activity." (PMID 30240750, 2018). "In summary, the mechanisms and potential therapeutic value of ESRP1 in melanoma require further investigation." (PMID 40046628, 2025). "ESRP1 expression status of melanomas played a significant role on cytolytic activity and in influencing survival of patients (ESRP1-low patients had better outcome)." (PMID 34439247, 2021). "In melanoma, patients with a lower expression of ESRP1 expressed mesenchymal markers and higher level of immune cytolytic activity and experienced better survival rate." (PMID 34285922, 2021). "We then analyzed the correlation between the level of ESRP1 and clinicopathologic features in melanoma." (PMID 32964032, 2020). "Studies have classified TCGA melanoma cases into ESRP1-low,–truncated and–full-length groups based on ESRP1 expression." (PMID 32467669, 2020). "In fact, a report show that altered expression and splicing of ESRP1 in malignant melanoma correlates with epithelial–mesenchymal status." (PMID 31868203, 2020). "However, when studying AS in the context of checkpoint immunotherapy, both in BC and melanoma, we found that response specific ASEs were most frequent in cancer cells where they were, at least in part, regulated by the splicing factor ESRP1." (PMID 41273175, 2025). "Further investigation on the role of ESRP1 in prostate cancer and melanoma are also warranted." (PMID 38110955, 2023). "In melanoma, the lower the expression of ESRP1, the longer the patient’s survival." (PMID 32467669, 2020). "ESRP1 acts as a master regulator of EMT in melanoma and somatotroph adenomas." (PMID 28333948, 2017). "Thus, our assay detects all transcript variants that use the regular ESRP1 start codon and does not identify variants that exist at other positions like the variant from melanoma." (PMID 27650542, 2016). "Silencing of ESRP1 significantly decreased the expression of CD44 isoforms containing exon v6 in human MB and LH cells derived from melanoma lymph node metastases." (PMID 38106992, 2023). "Although ESRP1 in cancer is primarily documented to be involved in EMT and metastasis, an in silico analysis found ESRP1 to be a target of interest in overcoming immune evasion in melanoma." (PMID 38815867, 2024).
melanoma (continued). "Further in this study, it has been shown that ESRP1 is epigenetically silenced in human melanoma brain metastasis, and high expression of CD44 containing exon v6 in early stages is a significant predictor of melanoma brain metastasis development." (PMID 38106992, 2023). "Increased PD-1, PD-L1, PD-L2 and CTLA-4 expression was also found in melanomas with robust EMT induced by a lack of epithelial splicing regulatory protein 1 (ESRP1) expression." (PMID 36823234, 2023). "E.g. the majority of melanoma highly express only the last four exons 13-16 that presumably do not generate ESRP1 protein with normal function." (PMID 27650542, 2016).
colorectal cancer (18 papers, 2016 to 2024). A primary or metastatic malignant neoplasm that affects the colon or rectum. "According to Mager LF, the reduced ESRP1 level leads to impaired intestinal barrier integrity, increases susceptibility to colitis, and alters colorectal cancer development." (PMID 32964032, 2020). "In mice, reduced ESRP1 function leads to impaired intestinal barrier integrity, increased susceptibility to colitis and altered colorectal cancer (CRC) development." (PMID 28975893, 2017). "We thus aimed at clarifying the role of ESRP1 in Colorectal Cancer (CRC) by performing loss- and gain-of-function studies, and evaluating tumorigenesis and malignancy with in vitro and in vivo approaches." (PMID 28052020, 2017). "ESRP1 expression has been reported to have both protumor and antitumor roles in colorectal cancer in vivo, but these studies were done in immunocompromised mouse models." (PMID 38815867, 2024). "ESRP1 expression was increased in colorectal cancer cells expressing wild-type full-length adenomatous polyposis coli (APC) and was correlated with APC levels in colorectal cancer primary tumors." (PMID 38110955, 2023). "Further studies are warranted to validate the prognostic significance and role of ESRP1 in colorectal cancer." (PMID 38110955, 2023). "For instance, in colorectal cancer, an elevated level of ESRP1 promotes cancer progression by actuating fibroblast growth factor signaling." (PMID 34362878, 2021). "We have previously shown that elevated expression of ESRP1 in colorectal cancer cells can drive tumor progression." (PMID 34439247, 2021). "Our data provide further insights into factors affected by and entwined with ESRP1 in colorectal cancer." (PMID 31963158, 2020). "In colorectal cancer, we have previously shown that aberrantly high ESRP1 expression can drive tumor progression." (PMID 31963158, 2020). "ESRP1 has been shown to support anchorage-independent growth of colorectal cancer cells and promote metastasis formation in vitro." (PMID 32706839, 2020). "In order to unveil the mechanisms by which ESRP1 can modulate cancer traits, we searched for proteins affected by modulation of Esrp1 in two human colorectal cancer cell lines, HCA24 and COLO320DM, by proteomics analysis." (PMID 31963158, 2020). "Further experiments on biopsies taken from patients with inflammatory bowel disease or colorectal cancer revealed that these patients had lower levels of ESRP1 compared to healthy individuals." (PMID 28975893, 2017). "ESRP1 was identified in some tumors as good or worse predictor of outcome, but in colorectal cancer (CRC) the prognostic value of ESRPs and relation with mesenchymal splice variants is not clear." (PMID 27650542, 2016). "In colorectal cancer, opposing roles of ESRP1 have been reported." (PMID 38110955, 2023). "ESRP1 was found to suppress tumorigenic potential in vivo, and the levels of ESRP1 mRNA measured using real-time quantitative reverse transcription-polymerase chain reaction correlate with favorable outcomes, suggesting that ESRP1 plays a tumor-suppressive role in colorectal cancer." (PMID 38110955, 2023). "High ESRP1 expression may thus stimulate growth of cancer epithelial cells in the colon as well as at distant sites, and promote colorectal cancer progression." (PMID 28052020, 2017). "However, upregulation of ESRP1 is correlated with fewer metastasis and better prognosis in pancreatic ductal adenocarcinoma, and acts a tumor suppressor in colorectal cancer, reflecting the cell type-specific nature of cancer genes." (PMID 28333948, 2017). "High ESRP1 expression may thus stimulate growth of cancer epithelial cells and promote colorectal cancer progression." (PMID 28052020, 2017).
prostate carcinoma (18 papers, 2013 to 2026). A carcinoma that arises from epithelial cells of the prostate gland. "Genome analyses of prostate tumours have revealed amplification of the ESRP1 gene (encoding the Epithelial Splicing Regulator Protein 1) to be associated with early onset aggressive prostate cancer." (PMID 37752235, 2023). "In hormone-dependent cancers such as breast and prostate cancers, ESRP1 expression was shown to be associated with steroid hormone signaling." (PMID 38110955, 2023). "Early onset of an aggressive subgroup of prostate cancer was found to be associated with the expression of ESRP1, indicating that ESRP1 is a potential prognostic marker in prostate cancer." (PMID 32964032, 2020). "In prostate cancer, integrative genomic analyses of prostate tumors identified that amplification of ESRP1 is associated with early-onset aggressive prostate cancer and high ESRP1 expression correlates with a more proliferative gene expression profile." (PMID 38110955, 2023). "In addition, several immunohistochemical analyses demonstrated that ESRP1 expression is significantly associated with poor prognosis in prostate cancer, suggesting that ESRP1 plays a pro-tumorigenic role." (PMID 38110955, 2023). "Recent data have identified an important mechanism controlling ESRP1 and ESRP2 expression within prostate cancer cells that is linked to disease progression." (PMID 37752235, 2023). "RNA-sequencing data from human prostate cancer showed that ESRP1 expression is significantly downregulated following androgen deprivation therapy." (PMID 38110955, 2023). "Further meta-analysis of prostate cancer TCGA data show down-regulation of EMT pathways in primary prostate tumours expressing high levels of ESRP1." (PMID 37752235, 2023). "Analysis of ESRP1/ESRP2 protein staining in thousands of prostate tumours show that levels of ESRP1/ESRP2 proteins are highest in prostate cancers that are also positive for the TMPRS22-ERG genetic fusion." (PMID 37752235, 2023). "We suggest that the origin of prostate cancer within epithelial cells, and the subsequent association of ESRP1 and ESRP2 expression with more aggressive disease progression, identify ESRP1 and ESRP2 as lineage survival oncogenes." (PMID 37752235, 2023). "For example, a splice isoform is produced from the MAP3K7 gene (that encodes a mitogen activated protein kinase enzyme) that skips exon 12 in response to ESRP1/ESRP2 depletion in prostate cancer cells." (PMID 37752235, 2023). "Our data show a striking link between nuclear ESRP expression and adverse features in prostate cancer and identifies expression of ESRP1 and/or ESRP2 as independent prognostic markers with a potential for routine application." (PMID 33339518, 2020). "We tested 112 well-characterized RBPs and found that expression of ESRP1/2 in prostate cancer cells decreased in response to treatment by pharmacological inhibitors of AR." (PMID 32820253, 2020). "ESRP1 has recently been shown to be amplified in an aggressive subgroup of early onset prostate cancer, but how this contributes to disease progression has been not well understood." (PMID 31478829, 2019). "Because of their low normal endogenous expression profiles, we selected PC3 and DU145 cells to study the effects on prostate cancer cells of ESRP1/ESRP2 protein up-regulation." (PMID 31478829, 2019). "We next investigated the effects of ESRP1/2 expression on the biology of prostate cancer cells in vivo." (PMID 31478829, 2019). "Similarly, ESRP1 has been suggested to aggravate prostate cancer progression and independently predicts poor prognosis of prostate cancer patients." (PMID 39550559, 2024).
prostate carcinoma (continued). "Although the ESRP1 gene is located on chromosome 8 close to the MYC oncogene (an important oncogene that is also frequently amplified in prostate cancer), ESRP1 amplification can be observed in prostate tumours independently of MYC alterations, indicating that it is not a bystander event." (PMID 37752235, 2023). "Indeed, MYC-independent ESRP1 amplification in early onset prostate cancer correlates with more advanced cancer histology and high mitotic activity of tumour cells, and is also predictive of a shorter time to disease recurrence." (PMID 37752235, 2023). "Similarly, ESRP1 was considered avital SF that leads to the progression and metastasis in pancreatic and prostate cancer." (PMID 32617077, 2020). "Our group recently identified ESRP1 to be significantly overexpressed in prostate cancer using an RNA expression screening approach and found that high ESRP1 expression detected by immunohistochemistry (IHC) was an independent predictor of a shorter time to biochemical recurrence." (PMID 33339518, 2020). "Interestingly, when ESRP1/2 is silenced in prostate cancer cells, the DHT- or casodex-mediated increase in the invasion rate is completely abolished." (PMID 32820253, 2020). "Four different multivariate analyses were applied to evaluate whether ESRP1 or ESRP2 expression as well as our ESRP1/ESRP2 score is a statistically independent prognostic marker in all prostate cancers and the subset of ERG-negative and ERG-positive cancers." (PMID 33339518, 2020). "In prostate cancers, nuclear ESRP1 and ESRP2 staining was more common and also more intense." (PMID 33339518, 2020). "(E) Western blot analysis of ESRP1 levels in prostate cancer cell lines." (PMID 31478829, 2019). "The splicing patterns of NUMB exon 3, MYO1B exon 23 and other ESRP-target exons can be experimentally modulated either by depleting ESRP1 and ESRP2 protein levels in prostate cancer cells, or by using drugs like Casodex to interfere with AR signalling." (PMID 37752235, 2023). "Global RNAseq studies have identified multiple splicing targets for ESRP1 and ESRP2 in prostate cancer cells." (PMID 37752235, 2023). "Expression levels of ESRP1 and ESRP2 genes also decrease in response to enzalutamide, a drug blocking AR function in prostate cancer cells." (PMID 37752235, 2023). "Treatment of cultured prostate cancer cells with Casodex and enzalutamide model the molecular changes that occur during ADT, and has established a clear link between ESRP1/ESRP2 and androgens." (PMID 37752235, 2023). "This study was undertaken to estimate the impact of ESRP1 and ESRP2 alterations on prostate cancer patient prognosis." (PMID 33339518, 2020). "In conclusion, ESRP1 is an important factor that directly affects genes that regulate the epithelial-mesenchymal transition (EMT) and promote prostate cancer invasion and metastasis." (PMID 33194621, 2020). "The ESRP1/ESRP2 score analysis showed a striking combined impact of combined ESRP1 and ESRP2 expression on prostate cancer prognosis." (PMID 33339518, 2020). "Our study identifies high expression of ESRP1 and ESRP2 as strong and statistically independent prognostic markers in prostate cancer." (PMID 33339518, 2020). "This is in line with one meta-analysis describing significant upregulation of ESRP1 and ESRP2 mRNA in 719 analyzed prostate cancers from 11 previous studies compared to normal prostate tissue." (PMID 33339518, 2020). "In prostate cancer, a meta-analysis reported significant up-regulation of ESRP1 and ESRP2 mRNAs in 719 prostate cancers from 11 previous studies including normal and malignant prostate tissues." (PMID 33339518, 2020). "Over-expression of both ESRP1 and ESRP2 (either alone or together) in PC3 cells also significantly slowed growth of prostate cancer xenografts in vivo." (PMID 31478829, 2019). "Over-expression of (E) ESRP1, (F) ESRP2, or (G) both ESRP1 and ESRP2 in PC3 cells significantly slowed the growth of prostate cancer xenografts in vivo." (PMID 31478829, 2019).